OR6C2 (olfactory receptor family 6 subfamily C member 2)
Description:
Odorant receptor.
Synonyms: OR6C67
Tractability: Antibody: UniProt places it where antibodies can reach, with medium confidence; UniProt predicts a signal peptide or a membrane-spanning region; its Gene Ontology location is reachable by antibodies, with medium confidence.
Gene: Protein-coding gene on chromosome 12 (55,444,069 to 55,453,347, forward strand). Ensembl gene ENSG00000179695.
Subcellular location: Cell membrane
Pathways (Reactome):
Sensory Perception: Expression and translocation of olfactory receptors
Gene Ontology:
Molecular function: olfactory receptor activity; G protein-coupled receptor activity
Biological process: sensory perception of smell; detection of chemical stimulus involved in sensory perception of smell; G protein-coupled receptor signaling pathway
Cellular component: membrane; plasma membrane
Genetic constraint (gnomAD): Loss-of-function variants: 0 observed, 0.26 expected, observed/expected ratio (o/e) 0, 90% interval 0 to 1.87. That is too few expected variants to judge how well the gene tolerates losing a copy. Missense variants: 426 observed, 377.7 expected, observed/expected ratio (o/e) 1.13, 90% interval 1.04 to 1.22. Synonymous variants: 142 observed, 138.64 expected, observed/expected ratio (o/e) 1.02, 90% interval 0.89 to 1.18.
Homologues: Orthologues: macaque OR6C2 (96% identical), pig OR6C2 (90% identical), mouse Or6c2 (90% identical), rat Or6c2 (89% identical), rabbit OR6C2 (86% identical). Paralogues in human: OR6C68 (75% identical), OR6C74 (69% identical), OR6C76 (68% identical), OR6C75 (66% identical), OR6C6 (65% identical), OR6C65 (65% identical), OR6C3 (64% identical), OR6C4 (64% identical), OR6C70 (64% identical), OR6C1 (64% identical), OR2AP1 (62% identical), OR6S1 (45% identical), and 6 more.
Diseases named in the same sentence as OR6C2 in open-access papers:
OR6C2 is named in the same sentence as 1 disease in open-access papers, as found by Europe PMC text mining. Sharing a sentence is not in itself a finding about the gene and the disease.
OR6C2 shares sentences with these, for which no sentence is quoted: glioma (1 paper).